RNU6-1198P (RNA, U6 small nuclear 1198, pseudogene)
Gene: Small nuclear RNA gene on chromosome 7 (73,507,208 to 73,507,274, forward strand). Ensembl gene ENSG00000252713.
Homologues: Orthologues: chimpanzee U6 (99% identical), dog U6 (78% identical), mouse Gm26411 (75% identical), mouse Gm23207 (72% identical). Paralogues in human: RNU6-1289P (87% identical), RNU6-1304P (85% identical), RNU6-188P (85% identical), RNU6-524P (85% identical), RNU6-689P (85% identical), RNU6-1311P (84% identical), RNU6-207P (84% identical), RNU6-333P (84% identical), RNU6-477P (84% identical), RNU6-532P (84% identical), RNU6-742P (84% identical), RNU6-768P (84% identical), and 1282 more.